S100A6 (S100 calcium binding protein A6)
Diseases named in the same sentence as S100A6 in open-access papers (continued):
Sharing a sentence is not in itself a finding about the gene and the disease.
tumor (continued). "This study proposes a novel and important function of S100A6 in regulating MDM2 that directly affects the growth of tumor cells and their sensitivity to chemotherapy, which is of high value in clinical use." (PMID 37217945, 2023). "In particular, we noticed that COL1A2, LAMB3, LOX, LTBP2 and S100A6 were significantly upregulated in tumor specimens, when compared with normal tissue." (PMID 35340765, 2022). "Then, the values of S100A6 expression in 4 tumor samples were considerably higher than that in matching normal samples in TCGA cohort (p = 0.029)." (PMID 35432196, 2022). "Elevated levels of S100A6 have been observed in epithelial cells, fibroblasts, and several types of tumor cells." (PMID 36613714, 2022). "Elevated S100A6 levels have been detected in many tumours and are closely related to poor differentiation." (PMID 34060533, 2021). "In our study, the results showed that the expression of S100A6 was significantly upregulated in HCC tissues than in para-tumor tissues." (PMID 33815482, 2021). "The gene expression profile analysis demonstrated that the levels of S100A4/S100A6/S100A10/S100A11/S100A13/S100P were higher in tumor than in normal liver samples." (PMID 33815482, 2021). "Given that it is responsible for tumor occurrence and metastasis, S100A6 is a promising therapeutic target to treat PC." (PMID 34527585, 2021). "The most upregulated genes in PDAC include SPINK1, known for contributing towards increased tumor proliferation and poor cancer prognosis; TFF1, which facilitates PDAC metastasis; and S100A6, a key diagnostic marker for PDAC." (PMID 35178072, 2021). "It was reported that S100A6 was overexpressed in HCC tissues compared with non-tumor tissues and the expression of S100A6 correlated with poor differentiation." (PMID 33815482, 2021). "It was found that the level of S100A6 was higher in the HCC tissues than in theadjacent non-tumor liver specimens." (PMID 33335992, 2020). "Protein S100A6 has been described in a limited number of cell types in adult normal tissues and in several tumor cell types." (PMID 32366023, 2020). "As a result, we found higher mRNA and protein levels of S100A6 inHCC tissues than in the adjacent non-tumor liver tissues." (PMID 33335992, 2020). "S100A6 functions in in cell proliferation, cytoskeletal dynamics, and tumorigenesis, thus promoting cell division and tumor growth." (PMID 29897930, 2018). "Metastatic fibroblasts also express two S100 family proteins, S100A10 and S100A6, which are important in creating inflammation for tumor growth and metastases." (PMID 30383866, 2018). "As a member of S100 protein family, S100A6 is highly expressed in epithelial cells, fibroblasts and in several types of tumor cells, which can regulate the cellular function of proliferation, apoptosis, cytoskeleton dynamics, tumorigenesis." (PMID 30558666, 2018). "The proteins S100A6 and 14-3-3 zeta/delta were also recently identified as abundant proteins in tumor interstitial fluid and cancerous tissue of CCA patients." (PMID 30440021, 2018). "In line, S100 family members, including S100A6, have been demonstrated to regulate critical processes such as tumor growth, metastasis, angiogenesis and immune evasion." (PMID 27709523, 2016). "Similar to the human tumor expression patterns, this analysis also showed a significantly up-regulated S100A6 expression in CCA tumor tissue compared to normal liver tissue of untreated or tumor-bearing mice as well as the tumor microenvironment." (PMID 27709523, 2016). "Postoperative S100A6 concentrations were similar in patients with complete vs. incomplete tumor resection and in patients with well-differentiated vs. undifferentiated tumors." (PMID 27709523, 2016). "As such, S100A6 was shown to be significantly up-regulated in the tumor tissue of cutaneous melanoma, colorectal adenocarcinoma, stomach and thyroid cancer, astrocytoma or pancreas ductal adenocarcinomas." (PMID 27709523, 2016).
tumor (continued). "To further confirm the correlation, we detected the expression of CXCL14 and S100A6 in the subcutaneous xenograft tumor tissues by immunohistochemical analysis." (PMID 25760073, 2015). "Our results showed that the mRNA levels of S100A6 were elevated in the tumor tissues than in the normal tissues (P < 0.01)." (PMID 25760073, 2015). "In this study, we found with knock-down of S100A6, the tumor cells growth was suppressed in vitro and in vivo." (PMID 25760073, 2015). "In both spheroids and tumour xenografts, S100A6 protein stained homogeneously, in contrast to the acid-induced behaviour observed in vitro during our discovery phase." (PMID 26658462, 2015). "Together, our data showed that the expression level of S100A6 had a significant correlation with tumor size, Fuhrman Grade, TNM stage and metastatic status." (PMID 25760073, 2015). "Previous studies on telomerase-inhibited tumor cell lines identified the peak at 10.1 kDa as the corresponding S100A6 protein." (PMID 22828447, 2012). "The mRNA expression levels of S100A6 were higher (5.884 ± 6.988) than non-tumor tissues (2.883 ± 1.687, P < 0.05)." (PMID 22681645, 2012). "Clinically, S100A6 expression is significantly correlated with two parameters; lymphatic permeation and Duke’s tumor status." (PMID 23166536, 2012). "Our immunohistochemical analysis showed cytoplasmic and/or nuclear staining of S100A6, predominantly in tumor cells of endometrioid EmCa." (PMID 21305022, 2011). "S100A6 is found in serum in concentrations that correlate with experimental tumor burden and with clinical disease stage." (PMID 19888321, 2009). "The human tumor-origin of the S100A6 was established for the model, and the serum concentration of S100A6 correlated with the amount of experimental cancer present." (PMID 19888321, 2009). "The presence of tumor-derived S100A6 protein in serum was further studied as a candidate biomarker using antibody-based analyses." (PMID 19888321, 2009). "Further clinical relevance was demonstrated through discovery of the potential for serum S100A6 to correlate with tumor burden using human clinical study sets." (PMID 19888321, 2009). "Ten animals each from tumor-bearing and control groups were bled and removed from study at each time point; serum S100A6 level was quantified by ECLISA for all study mice." (PMID 19888321, 2009). "Using a human xenograft model simulating disseminated growth of OVCA, serum S100A6 level, derived from the tumor tissue, directly correlated with increasing tumor burden and disease progression." (PMID 19888321, 2009). "Using a custom anti-human S100A6 antibody, C1, a 10.5 kDa band corresponding to the molecular weight of S100A6 was detected in pooled sera collected 4 weeks p.i. from tumor-bearing mice used for initial MS analyses." (PMID 19888321, 2009). "The correlation between tumor burden and the serum S100A6 level in specimens from these same SKOV-3-Luc-injected mice was sought next." (PMID 19888321, 2009). "S100A6 significantly correlated with tumours arising in the supratentorial region of the brain (P<0.001) and S100A4 correlated with age at diagnosis under 3 years (P=0.038)." (PMID 18781180, 2008). "S100A6 significantly correlated with supratentorial tumours (P<0.001) and S100A4 with patients under the age of 3 years at diagnosis (P=0.038)." (PMID 18781180, 2008). "S100A6 is involved in inflammation, tumor development, apoptosis and calcium homeostasis." (PMID 38334598, 2024). "Among them, S100A6+ tumor cells play a crucial role in metastasis." (PMID 39095854, 2024). "Lysozyme has been shown to have inhibitory effects on tumour proliferation through both direct and indirect modulation of host immunity, inducing interferon production, as well as interruption of both interleukin and S100A6 signalling." (PMID 38505585, 2024). "S100A6 is expressed in tumor diseases and stem cells and has a potential biomarker role." (PMID 37670392, 2023).
tumor (continued). "S100A6 and its family members also participate in the regulation of tumor cell differentiation." (PMID 37670392, 2023). "Overexpressed MDM2 attenuated tumor growth suppression by S100A6." (PMID 37217945, 2023). "It was found that S100A6 suppressed the tumor growth and enhanced its sensitivity to paclitaxel." (PMID 37217945, 2023). "When evaluating the impact of S100A6 on tumor invasion, migration, and other functions related to the cell bone ring, research on regulating physical and chemical environmental conditions is also valuable and may identify potential therapeutic targets." (PMID 37670392, 2023). "S100A6 is expected to bring about novel changes in the diagnosis and treatment of tumor diseases." (PMID 37670392, 2023). "Finally, the removed tumor tissue was subjected to western blot to verify the expressions of S100A6 and MDM2." (PMID 37217945, 2023). "Together with S100A4, S100A6 is the most widely documented protein in the S100 family and is a potential biomarker of tumor invasiveness in proteomics in MM and other cancers, and their combined involvement in breast cancer cell proliferation and motility was recognized early." (PMID 35873564, 2022). "Moreover, S100A6 gene is located in human chromosome 1q21, where frequent chromosomal rearrangements occur in neoplasia." (PMID 35432196, 2022). "In addition, S100A6 was expressed significantly differently in PC tissues with different tumor grades." (PMID 35432196, 2022). "S100A6 was shown to be highly expressed in PC compared to non-tumor tissues." (PMID 35432196, 2022). "The involvement of S100A6 in the tumor immune microenvironment (TIME) was assessed by CIBERSORT." (PMID 35432196, 2022). "Previous epigenetic studies emphasized the relationships between methylation of the promoters of SSP1 and S100A6 and expression of these genes, but few studies examined the relationship of SPP1 and S100A6 expression with global methylation levels of tumor cells." (PMID 34857857, 2021). "Inhibition of S100A6 reduces the invasiveness and proliferation of PC cells, and the possible mechanisms are that S100A6 activity may directly or indirectly regulate tumor proliferation/invasion/metastasis-related genes." (PMID 34527585, 2021). "S100A6 has a tumor-promotional effect in a variety of cancers." (PMID 34148033, 2021). "Additionally, the human HCC tissues exhibited a highmRNA level of S100A6 when compared with the adjacent non-tumor liver tissues." (PMID 33335992, 2020). "For instance, pairwise comparison of primary tumor cell line #1 with recurrent tumor cell line #3 identified a cluster (Cluster #7) distinguished by high expression of mesenchymal genes, including Vimentin, S100A6, and Timp1." (PMID 33024122, 2020). "Accordingly, IHC analysis revealed that S100A6, lumican, plastin-2 and 14-3-3 zeta/delta were expressed in the cytoplasm of tumor cells while vimentin was found mainly in the cytoplasm of fibroblasts in periductal fibrotic tissue and tumor stroma." (PMID 30440021, 2018). "We analyzed if, in contrary to initial S100A6 levels, postoperative S100A6 concentrations might have a better value for determination of tumor characteristics or success of surgery." (PMID 27709523, 2016). "Several lines of evidence found that S100A6 level increased upon stress conditions such as ischemia, mechanical force, irradiation or oxidative stress, which were most likely the tumor microenvironment." (PMID 25760073, 2015). "Because of the correlation and regulation of chemokine, we examined whether S100A6 promoted tumor growth by inhibition of ccRCC cell apoptosis." (PMID 25760073, 2015). "Similarly, S100A6 protein levels were higher in tumor tissues compared to their normal counterparts." (PMID 25760073, 2015). "Knockdown of S100A6 inhibited cell proliferation in vitro and tumor growth in vivo." (PMID 25760073, 2015).
tumor (continued). "However, the molecular mechanism, how glyphosate contributes in tumor promotion, and regulation of S100A6, S100A9, and SOD 1 remain elusive and require more detailed analysis of the mechanism." (PMID 24073338, 2013). "When tumor burden (cell number) was plotted against serum S100A6 protein concentration in these animals, results indicated a highly significant correlation (r = 0.79, p<0.0001); serum S100A6 concentration was greater as the tumor burden increased over time for animals given SKOV-3-Luc." (PMID 19888321, 2009). "Tumor burden was correlated with the presence or level of serum protein S100A6 in the model, which thereby could be considered as a putative biomarker." (PMID 19888321, 2009). "In addition, a system was sought to correlate quantity of serum S100A6 and tumor burden in the model." (PMID 19888321, 2009). "Consequently, discovery of S100A6 as a surrogate for tumor burden in the model appears to have been predictive of the findings in women with advanced stage OVCA." (PMID 19888321, 2009). "Longitudinal study revealed that serum S100A6 concentration is directly related to tumor burden predictions from an inverse regression calibration analysis of data obtained from a detergent-supplemented antigen capture immunoassay and whole-animal bioluminescent optical imaging." (PMID 19888321, 2009). "To determine whether the overexpression of S100A6 occurred in tumours, which also overexpressed annexin 2, we investigated the expression of annexin 2 in this cohort (56 cases had sufficient material for evaluation)." (PMID 19724273, 2009). "S100A6 was identified in the sera of mice with human OVCA using an MS/MS-based bottom-up proteomics strategy in an attempt to discover candidate biomarkers derived from tumor mass." (PMID 19888321, 2009). "The hypermethylation observed for S100A6 was less pronounced in primary tumours (affecting a limited number of CpG residues) than cell lines and further work is needed to determine whether this level of methylation leads to transcriptional silencing." (PMID 17579622, 2007). "Although, the absence of S100A6 expression seen in all tumours was confirmed in the LNCaP cell line and its variants, other metastatic cell lines such as Du145 and PC3 (and its variants), were shown to express S100A6." (PMID 15280928, 2004). "In astrocytic tumours S100A6 protein expression correlates with tumour grade." (PMID 15280928, 2004). "Therefore, we will introduce S100A6 in combination with cell proliferation and tumor diseases." (PMID 37670392, 2023). "Thus, we found that the knockdown of S100A6 suppressed cell and tumor growth in vivo." (PMID 25760073, 2015). "Collectively, these data indicate that HCC tumor cells can be stratified into three distinct subtypes, characterized by the expression of ARG1, TOP2A, and S100A6, respectively." (PMID 39095854, 2024). "We identified three subtypes in tumor cells, including ARG1+ metabolism subtype (Metab-subtype), TOP2A+ proliferation phenotype (Prol-phenotype), and S100A6+ pro-metastatic subtype (EMT-subtype)." (PMID 39095854, 2024). "Gene expression analysis showed a 31.5-fold increase in S100A6 gene expression (and a 14.7-fold increase in S100A4 gene expression) in these cells compared with most tumor cells." (PMID 37670392, 2023). "There was less suppression of tumor growth in mice with MDM2 and S100A6 co-transfected cells than in those with S100A6-transfected cells." (PMID 37217945, 2023). "Clusters 3 and 5, mainly enriched in the tumor and interface zones, were characterized by genes S100A4, AP1S2 and S100A6 that defined monocytes." (PMID 37644609, 2023). "Eleven DEGs were observed between tumor and adjacent normal tissue including S100P, PHGR1 and S100A6." (PMID 36253784, 2022). "Compared with para-cancer tissues, the expression levels of S100A4/S100A6/S100A10/S100A11/S100A13/S100A14/S100P were higher in HCC tissues, while the expression levels of S100A8/S100A9/S100A12 were decreased in tumor tissues." (PMID 33815482, 2021).
tumor (continued). "The expressions of S100A6 in human HCC and adjacent non-tumor liver specimens weredetected using immunoblotting and quantitative PCR (qPCR)." (PMID 33335992, 2020). "61, 83 and 83% of tumours showed moderate to strong staining for S100A4, S100A6 and S100A14, respectively, whereas only 22% were positive for S100A2." (PMID 31123345, 2019). "S100A6 mRNA expression levels were analyzed in human and murine CCA tumor samples, using semi-quantitative reverse transcriptase PCR." (PMID 27709523, 2016). "S100A6 mRNA expression levels were significantly up-regulated in tumor samples of CCA patients and in tumor tissue of a CCA mouse model." (PMID 27709523, 2016). "Meghnani and colleagues also reported an up‐regulation of the RAGE ligands S100B, S100A2, S100A4, S100A6 and S100A10 in RAGE overexpressing tumours." (PMID 26928771, 2016). "Our data show that several S100 genes, i.e. S100A4, S100A6, S100A10, S100A8, and S100A9, are expressed at very high levels in both tumor cells and TAMs." (PMID 27215396, 2016). "We compared the expressions of S100A6 among sub-groups of age, gender, BMI, Fuhrman grade, TNM stage, and tumor diameter." (PMID 25760073, 2015). "The expression pattern of S100A6 and S100A9 expressions was found to be considerably enhanced in some tumor tissues like hepatocellular carcinoma, lung cancer, colorectal cancer, and melanoma." (PMID 24073338, 2013). "S100A6 and S100A11 can discriminate significantly between the two primary tumor entities, CRC and HCC, whereas S100A6 allows the discrimination of metastases and HCC." (PMID 19048101, 2008). "Endothelial cells exposed to S100A13 and S100A6 display increased angiogenic activity through VEGF and ERK pathway activation, linking S100 signaling to neovascularization and nutrient supply within the tumor." (PMID 41404073, 2025). "However, in the tumor array, positive correlations were observed between S100A14 and S100A2 (R = 0.50), S100A4 (R = 0.55), S100A6 (R = 0.45), S100A7 (R = 0.47), S100A11 (R = 0.65), S100A16 (R = 0.57) and S100P (R = 0.66)." (PMID 37627239, 2023). "Regardless of paclitaxel treatment, the tumor growth for mice with S100A6-transfected cells was obviously delayed in contrast to that with control-transfected cells." (PMID 37217945, 2023). "In addition, correlations were also noted in the tumor array between S100A11 and S100A2 (R = 0.54), S100A4 (R = 0.46), S100A6 (R = 0.49), S100A13 (R = 0.67), S100A14 (R = 0.65), and S100A16 (R = 0.78)." (PMID 37627239, 2023). "Although the expression level of S100A6 is significantly increased in human and mouse CCA tumor samples, the serum level of S100A6 is not changed in patients with CCA; therefore, it is not suitable for the diagnosis of CCA." (PMID 37670392, 2023). "KDELR3 was mainly expressed in tumor cells, IDH2 was mainly expressed in endothelial cells, S100A6 was mainly expressed in photoreceptor cells, ITPA was mainly expressed in endothelial cells and tumor cells, PARP8 was mainly expressed in T cells, and APRC1B was mainly expressed in endothelial cells." (PMID 35242144, 2022). "More specifically, several studies reported that increased expression of S100A6 promoted cell proliferation by regulating the expression of IL‐8, CDK5, CDK4, MCM7, Bcl2, and could be used as a marker of tumor aggressiveness in gastric cancers." (PMID 34857857, 2021). "S100A6 was upregulated in the central part of the tumor compared to the non-involved part of the bowel." (PMID 32422974, 2020). "To address whether our observation is relevant to the activation of S100A6 and S100A4 in tumours, we assessed the expression of pSTAT3 in PDAC specimens by IHC." (PMID 31123345, 2019). "In addition, fibroblast proliferation and mesenchymal cell proliferation were significantly enriched GO terms; the expression levels of TGFβ1, S100A6, PDGFA, and BMP7 were enriched in organoids (and tumor), compared with fetal retina." (PMID 30353124, 2018).